CRP (C-reactive protein)
Diseases named in the same sentence as CRP in open-access papers (continued):
Sharing a sentence is not in itself a finding about the gene and the disease.
infection (continued). "CRP is an acute-phase protein produced in response to acute conditions, primarily stimulated by IL-6 during the acute phase of inflammation or infection." (PMID 39525122, 2024). "Of previously established biomarkers for infection and inflammation, we found that CRP, WBC, and neutrophil counts increased in TB and CMTB compared to TBI and HC." (PMID 38933274, 2024). "This was originally explained with selection bias as the attending physicians had retrospectively assessed infection taking CRP into account." (PMID 39434093, 2024). "This infant exhibited elevated white blood cell count and CRP, indicating the presence of an infection-related inflammatory response." (PMID 38957388, 2024). "We evaluated laboratory parameters such as glycemia, creatinine, total protein, and C-reactive protein (CRP), as well as demographic data, primary kidney disease, donor type, comorbidities, and infection incidence." (PMID 39796484, 2024). "Of interest, these patients have elevated neutrophil-to-lymphocyte ratios, indicating inflammation, and importantly, elevated high-sensitivity C-reactive protein and interleukin-6 levels in the initial phases of the infection." (PMID 39355453, 2024). "When CRP was used to predict infection at a critical value of 150.00 mg/L on POD 3, the sensitivity and specificity were 61.90% and 78.90%, respectively." (PMID 38504206, 2024). "This aligns with the outcomes of the ROC curve analysis, which showed that IL-6 had the highest AUC value among all factors, including existing infection markers such as CRP and PCT." (PMID 39654974, 2024). "Neutrophil surface antigens CD11, CD14, CD64, and sCD14 (presepsin) are promising early infection markers that correlate well with CRP." (PMID 39858292, 2024). "This is consistent with observations that IL-6 is immediately synthesized in response to infection, activating an acute immune response and inducing CRP production by hepatocytes." (PMID 38709460, 2024). "CRP, an acute-phase protein, is generated in response to cytokine activation due to infection, ischemia, trauma, and other inflammatory stimuli." (PMID 39768925, 2024). "CRP was shown to be more sensitive and specific for the diagnosis of infection than ESR; it has high sensitivity in acute infections and low sensitivity in chronic infections." (PMID 38727451, 2024). "This was the case for CRP, which appeared patchily in the literature as of the 1980s, with studies initially focusing on CRP trends in the days following infection and surgery." (PMID 38543601, 2024). "In this case, changes in white blood cell count and C-reactive protein levels observed in pre-and post-operative blood tests further supported the effectiveness of emergency cervical cerclage in controlling infection and promoting postoperative recovery." (PMID 39659804, 2024). "CRP, commonly used as a biomarker for acute inflammatory states, exhibits increased plasma concentrations parallel to the infection’s clinical course with a decrease indicating resolution." (PMID 38667467, 2024). "Traditional CRP tests measure protein levels that indicate acute inflammation, such as infection or injury." (PMID 38983990, 2024). "Other studies have shown similar associations, where elevated CRP and WBC levels were predictive of infection-related preterm birth." (PMID 39569252, 2024). "In cases of acute abdomen, POC CBC and CRP can aid in diagnosing severe infections, ruling out appendicitis." (PMID 38434607, 2024). "The white blood cell count and levels of C-reactive protein and procalcitonin differed significantly between the infection and non-infection groups (P = 0.020, P = 0.011, and P = 0.003, respectively), although the absolute difference in the medians were small." (PMID 36877734, 2023). "In light of our work, Kaiser’s calculator also lacks the values of laboratory markers of infection such as the serum concentrations of CRP and PCT, and CBC." (PMID 36834338, 2023).
infection (continued). "We previously demonstrated that high levels of the soluble Programmed Death-Ligand1 (sPD-L1) at the beginning of the infection correlated with low lymphocyte number and high C-reactive protein (CRP), longer length of stay (LOS), and death." (PMID 37959277, 2023). "CRP is one of the major acute-phase proteins which can increase relatively rapidly in response to infection or injury and is considered to be a reliable and accurate measure of inflammatory response." (PMID 37379302, 2023). "CRP had the second-highest diagnostic value, while ESR had the worst diagnostic value for infection with a specificity of only 54%." (PMID 36653805, 2023). "CRP increases early during infection, whereas alpha-1-acid glycoprotein (AGP), an acute phase protein, increases later and remains elevated longer than CRP." (PMID 38130330, 2023). "It does not have as well of an established role in spondylodiscitis, but it was found to be less sensitive than CRP and is only significantly elevated in patients with concurrent spondylodiscitis and other concurrent infections." (PMID 37483708, 2023). "For a prospective study using the DELIKT, comorbidity variables must either be assessed using a diagnosis list or asking the patient or be replaced by a surrogate parameter, such as the CRP for infection." (PMID 37061661, 2023). "According to a multicenter retrospective review of 2737 implants, a raised WBC, ESR, and CRP were only present in half of the cases of an SCS-related infection, suggesting a low sensitivity of these tests to detect infection." (PMID 37932816, 2023). "As an acute-phase-response protein, CRP levels begin to rise 10–12 h after infection exposure, continuing to climb for 24–48 h after infection exposure." (PMID 37176503, 2023). "Concentrations of CRP are increased in response to infection, injury and inflammation and mediated by regulation of the C1q component of the complement leading to pathogen opsonization that subsequently stimulates the synthesis of pro-inflammatory cytokines." (PMID 37513762, 2023). "Postoperative CRP>150 mg/L (at 3–5 days postoperatively) is the most sensitive biochemical indicator of infection, and patients with CRP levels lower than 135mg/L on the 4th day after surgery are less likely to develop postoperative infectious complications." (PMID 37744382, 2023). "A mismatch between CRP and PCT as a marker of infection was observed in 70 patients, of which 10% with CRP-/PCT+ and 25% with CRP +/PCT-." (PMID 36693048, 2023). "When patients are exposed to infection or tissue damage, CRP is synthesized by the liver, and then interacts with the immune system to participate in the defense against infection." (PMID 37576139, 2023). "Higher levels of CRP and procalcitonin were seen in neutropenic patients as it indicates severe infection and inflammatory response." (PMID 36923173, 2023). "Patients with peritoneal dialysis should prevent infection and other situations leading to high CRP of more than 10 mg/L." (PMID 37304869, 2023). "They would all have been detected using an ImmunoXpert ≥ 35, a Labscore threshold of 1 or 3, or PCT ≥ 0.5 ng/mL, whereas WBC ≥ 15 G/L or CRP ≥ 40 mg/L would have detected respectively only two and three of these infections." (PMID 37956117, 2023). "Whereas, CRP levels above 23 mg/L together with an NLR above 9.7 predicted an infection diagnosis with a sensitivity of 69% and a specificity of 84% with an OR of 25.59 (95% CI: 9.73–67.31)." (PMID 37016028, 2023). "There was also a correlation of CRP values on selected days with longer stay in the hospital and ICU, as well as a significant association with perioperative deaths and deaths due to infection." (PMID 36839578, 2023). "When inflammation or infection occurs, CRP concentrations rise rapidly and repair cellular tissues, reducing damage and increasing resistance to inflammation." (PMID 37296194, 2023).
infection (continued). "For the infection index, all patients had rapid c-reactive protein tests, and their median levels were 151.08 ± 70.35 mg/L." (PMID 37671399, 2023). "PCT and CRP have garnered attention as potential indicators of infection severity and response to treatment." (PMID 37821527, 2023). "CRP is one of the proteins released into the bloodstream in response to inflammation and is considered an early marker of infection and inflammation." (PMID 36668902, 2023). "Circulating CRP levels exhibit a drastic increase in the acute phase of an infection/injury, but often a constant and low‐grade increase in the presence of chronic inflammation." (PMID 37493001, 2023). "PSP demonstrated better predictive ability for ICU mortality in comparison to canonical biomarkers of infection as CRP, but similar to PCT." (PMID 37707744, 2023). "CRP is produced primarily by hepatocytes in response to tissue injury or infection, eliciting an inflammatory response." (PMID 38136185, 2023). "Nonetheless, potentially dangerous, IL-6-blocking regimens also diminish or abolish the increase of C-reactive protein (CRP) in cases with serious infections." (PMID 37304255, 2023). "They observed CRP elevations in only 59% of patients and abnormal leukocyte counts in 36% of infections." (PMID 38137098, 2023). "CRP levels are typically below 3 mg/L in healthy patients, from 10 to 100 mg/L during a mild infection, and as high as 500 mg/L in patients experiencing a severe inflammatory response." (PMID 36662693, 2023). "The NLR and CRP ratio can be considered a prognostic marker of the course of infection and hospitalization time." (PMID 36670722, 2023). "Although these medications can quickly return the levels of infection-related biomarkers (e.g., IL-6 and CRP) to normal levels, patients treated with these drugs are at risk of virus recurrence (such as Patient # 4)." (PMID 37894092, 2023). "Blood tests revealed a c-reactive protein (CRP) level of 32 mg/dL, White blood cell count of 25,300/μL, neutrophil count of 23,320/μL, and platelet count of 48,000/μL, and severe infection was diagnosed." (PMID 37417630, 2023). "CRP is an acute-phase inflammatory protein produced by the liver in conditions of inflammation and infection." (PMID 37108017, 2023). "Infection was effectively controlled by antibiotics treatment as evidenced by a decreased level of c-reactive protein (c-reactive protein 7.4 mg/L)." (PMID 37904403, 2023). "The threshold of levels of pre-infection CRP and pre-infection platelet count are 6.11 mg/L and 168 × 109/L respectively." (PMID 37864133, 2023). "Serum C-reactive protein, an acute chronotropic reactive protein elevated in the presence of infection, is second only to HCY in RF models in terms of relative importance." (PMID 37051146, 2023). "The reason for this inaccuracy is the simultaneous release of CRP due to surgery-related tissue damage as well as infection-related CRP release." (PMID 35943586, 2023). "The results showed that there were statistically significant differences in PCT and CRP levels among the different infection sites (P = 0.002 for PCT, P = 0.005 for CRP)." (PMID 37821527, 2023). "Blood indicators including ALT, AST, WBC, CRP and IL-6 indicated that both liver injury and systemic inflammation worsened as the infection progressed." (PMID 37587524, 2023). "To continue, CRP is an acute-phase protein and the most commonly used marker of infection in neonates." (PMID 36834338, 2023). "CRP plays an important role in the innate immune system, rising rapidly in response to infection and inflammation, declining sharply after the acute phase." (PMID 37476545, 2023). "The level of CRP, as a positive acute phase reactant, will increases when infection or inflammation occurs." (PMID 37277756, 2023).
infection (continued). "Concerning inflammatory biomarkers, increased procalcitonin and C-reactive protein (CRP) levels have been linked to a higher risk of death and severe infection by severe acute respiratory syndrome coronavirus 2 (SARS-CoV-2)." (PMID 38256320, 2023). "Regarding malnourished children with concurrent infection, most studies have focused, besides blood culture, on C-reactive protein and procalcitonin." (PMID 37892278, 2023). "C-reactive protein (CRP), an acute reactive protein produced by the liver, is an indicator whose level rapidly increases in response to acute inflammation and infection." (PMID 37709919, 2023). "Bacterial isolates were identified using standard microbiological techniques, and statistical analyses were performed to assess associations between infection localization, bacterial species, PCT, and CRP levels." (PMID 37821527, 2023). "PCT and CRP have received increasing levels of attention with regards to the diagnosis of infection." (PMID 37953798, 2023). "Medical intervention reducing CRP plays a significant role in PEW prevention for patients with infection or inflammation." (PMID 37304869, 2023). "In recent decades, CRP was recognized as an acute-phase reactant that increased in response to various inflammatory stimuli, such as infections, injuries, and autoimmune diseases." (PMID 37893085, 2023). "CRP testing is cost-effective and easily performed in most hospitals; therefore, CRP is a well-established marker of inflammation and infection." (PMID 36766476, 2023). "In order to analyze the diagnostic value of individual laboratory biomarkers in predicting infection, ROC analysis was performed for the following markers for inflammation of infectious origin: hBD2, CRP and PCT." (PMID 37296737, 2023). "CRP plays a key role in recognizing acute phase reactants released by infection, tissue damage, and inflammation mediated by the cytokine IL-6." (PMID 37114211, 2023). "Experimental evidence from gene-modified animals indicates that CRP exerts host protective functions in bacterial, especially pneumococcal, infections." (PMID 37885881, 2023). "Pathophysiologically, C-reactive protein and neutrophils are not only elevated when an infection occurs in the body but can also rise in pathologies with trauma and inflammation associated." (PMID 37763124, 2023). "C-reactive protein (CRP) is secreted by the liver in response to inflammation and inflammatory cytokines due to infection." (PMID 38057707, 2023). "Median baseline CRP levels in the infection group were 76 (56.2-91) mg/L vs 9.5 (3-16.6) mg/L in the asymptomatic group, p<0.001." (PMID 36895535, 2023). "Following infection, several acute-phase reactants, such as CRP, LDH, ferritin, and D-dimer, play a crucial role in inflammatory responses." (PMID 37293303, 2023). "We examined patients’ infection-related condition based on a body temperature ≥ 37.5 °C or elevated CRP or WBC from baseline in this study." (PMID 36650580, 2023). "IL-6 concentrations spike very early in the course of infection or inflammation, followed by an increase in hepcidin, then a rise in CRP and finally the release of AGP37." (PMID 37365154, 2023). "This would result in our measured CRP responses to vaccination being artificially high because infection with an actual pathogen would induce a larger magnitude CRP response." (PMID 38100425, 2023). "We have chosen to use it because it is a good analogue in rats for acute systemic inflammation (especially in infection), akin to C-reactive protein (CRP) in humans." (PMID 37907937, 2023). "One of the dogs that had a normal neutrophil count and elevated CRP also had a toe infection severe enough to warrant a treatment delay." (PMID 37163491, 2023). "CRP was originally identified as an acute-phase protein because a rapid increase in CRP is found at sites of infection or inflammation." (PMID 37893085, 2023).
infection (continued). "The concentration of CRP increases due to inflammatory conditions, such as infections, rheumatoid arthritis, and various heart illnesses." (PMID 38024833, 2023). "CRP acts as an acute phase plasma protein in response to inflammation or infection; it is regulated by proinflammatory cytokine stimulation such as tumor necrosis factor-alpha, interleukin-1 (IL-1), and IL-6." (PMID 36674837, 2023). "Because CRP values were obtained retrospectively, there were more values available for infants undergoing higher scrutiny for possible infection, but this again reflects current clinical practice." (PMID 37606448, 2023). "As we had data on all patients’ CRP values, the data on infection episodes with a CRP of 100 mg/l or higher were complete and assessed in the same way regardless of dialysis modality." (PMID 37314998, 2023). "CRP is an acute inflammatory protein that increases in the presence of injury, inflammation, or infection." (PMID 37342535, 2023). "CRP is an acute-phase reactant that is significantly elevated at the early stages of infection by mediation of inflammatory factors such as IL-6." (PMID 37362407, 2023). "This is because the infection stimulates the immune system to produce an inflammatory response, leading to an increase in CRP synthesis." (PMID 38005386, 2023). "A clinical trial has reported glutamine leads to an increase in the total lymphocyte count, CD8 +, CD4 +, complement IgA, IgG, C3 in immunocompromised patients and lowered the content of CRP as well as the risks of incision infections." (PMID 37566134, 2023). "The original discoverers of CRP felt that it was elicited by infection with Gram positive organisms." (PMID 36936978, 2023). "Nevertheless, a subset of patients who acquired infections during their ICU stay also displayed an alternative pattern characterized by a decline in CRP serum levels in the days preceding infection diagnosis (Pattern C)." (PMID 37834754, 2023). "Sensitivity and specificity of WBC counts and CRP values to diagnose postoperative infection are limited in the context of HIPEC." (PMID 36631814, 2023). "These events have been well-described together with MIS-c; specifically, C-reactive protein is an acute inflammatory protein that increases up to 1000-fold at sites of infection or inflammation and often precedes the onset of fever." (PMID 37765039, 2023). "Infection indicators such as white blood cells, CRP, and granulocytes were increased in 8 patients (8 cases, 47.1%)." (PMID 37881633, 2023). "The relatively short half-life is an advantage of both prealbumin and CRP proteins; therefore, they are sensitive indicators of infection." (PMID 36670722, 2023). "Of note, older patients had more severe infections, as indicated by the CRP levels, than the younger patients." (PMID 37099226, 2023). "Despite the fact that only 11 patients had at least one sign of infection, the median white blood cell count/mm3, median value of total neutrophils, and median value of C-reactive protein were above normal levels." (PMID 37887202, 2023). "High-sensitivity C-reactive protein (hs-CRP) is also a simple-to-measure biomarker that can be raised in both acute and chronic diseases and represents systemic inflammation, infection, or tissue damage in the body." (PMID 36829557, 2023). "CRP is a protein produced by the liver that acts as an early indicator of infection and inflammation in blood." (PMID 37415112, 2023). "It is well studied that some pathogens like Chlamydia pneumoniae, Helicobacter pylori, and cytomegalovirus are associated with AS, and the acute rise of C-reactive protein (CRP), which indicates infection, shows a strong positive correlation with AS." (PMID 36817159, 2023). "In contrast, CRP is more accessible but less specific for infection and often used as a marker of the level of systemic inflammation." (PMID 36399260, 2023).